ENSG00000200385
Gene: Small nucleolar RNA gene on chromosome 14 (37,720,425 to 37,720,561, forward strand). Ensembl gene ENSG00000200385.
Homologues: Paralogues in human: SNORA80E (74% identical), SNORA80A (68% identical), SNORA80B (68% identical), SNORA80D (68% identical), SNORA80C (65% identical).